FARS2 (phenylalanyl-tRNA synthetase 2, mitochondrial)
Diseases named in the same sentence as FARS2 in open-access papers:
FARS2 is named in the same sentence as 73 diseases in open-access papers, as found by Europe PMC text mining. Sharing a sentence is not in itself a finding about the gene and the disease. The quoted sentences say what the papers report.
developmental delay (6 papers, 2017 to 2025). "The patient with FARS2 gene mutation had intractable focal onset seizure since birth, hypotonia, and developmental delay." (PMID 37628333, 2023). "In human, a patient suffers with global developmental delay, dysarthria and tremor caused by a deletion at chromosome 6p25.1 includes all of exon 6 and parts of introns 5 and 6 of FARS2." (PMID 29558483, 2018). "She presented with developmental delay, encephalopathy, elevated CSF lactate, and abnormal respiratory enzymes, consistent with the clinical features reported for FARS2 defects." (PMID 28419689, 2017). "COXPD14 is an unusual autosomal recessive disorder caused by defects in FARS2 and is characterized by early-onset encephalopathy with or without epilepsy, developmental delay, high levels of lactate, and short or long lifetimes." (PMID 36155627, 2022). "Patient 4M is a 4‐year‐old boy with two heterozygous variants to the FARS2 gene c.737C > T (Thr210Met) and c.1268G > A (Arg387Gln) (p.T246M in 3DN is Thr210Met) who presented with nonspecific developmental delay and hypotonia." (PMID 28419689, 2017).
hereditary spastic paraplegia (5 papers, 2017 to 2024). Hereditary spastic paraplegias (HSP) comprise a genetically and clinically heterogeneous group of neurodegenerative disorders characterized by progressive spasticity and hyperreflexia of the lower limbs. "COXPD14, caused by mutation of the FARS2 gene, mainly manifests as three phenotypes: early onset epileptic encephalopathy, hereditary spastic paraplegia, and juvenile onset epilepsy." (PMID 38166857, 2024). "FARS2‐associated hereditary spastic paraplegia, later onset spastic paraplegia type 77, is a rarely neurodegenerative disease." (PMID 39342436, 2024). "For example, biallelic missense mutations in FARS2 have been linked to hereditary spastic paraplegia." (PMID 37274208, 2023). "We have previously shown that a missense homozygous mutation c.424G > T (p.D142Y) in the FARS2 gene is the cause of pure-form hereditary spastic paraplegia (HSP)." (PMID 35794642, 2022). "As a member of mt-aaRSs genes, FARS2 missense homozygous mutation c.424G > T (p.D142Y) found in a Chinese consanguineous family first built the relationship between pure hereditary spastic paraplegia (HSP) and FARS2 gene." (PMID 35794642, 2022). "In previous publications, patients with FARS2 deficiency were noted to have either (i) early-onset epileptic encephalopathy, (ii) autosomal recessive hereditary spastic paraplegia, or (iii) juvenile onset refractory epilepsy." (PMID 29126765, 2017). "Approximately 58 subjects with disease-causing variants of FARS2 have been reported, including 31 cases of early-onset epileptic encephalopathy, 16 cases of hereditary spastic paraplegia, 3 cases of juvenile-onset epilepsy, and 8 cases of unknown phenotypes." (PMID 38166857, 2024). "Approximately 58 subjects with disease-causing variants of FARS2 have been reported, including 31 cases of early onset epileptic encephalopathy, 16 cases of hereditary spastic paraplegia, 3 cases of juvenile-onset epilepsy, and 8 cases of unknown phenotype." (PMID 38166857, 2024). "Homozygous expression of a Fars2 mutation (p.Asp142Tyr), which severely compromises mt-PheRS aminoacylation activity and causes hereditary spastic paraplegia in humans, is embryonically lethal in mice during early gestation, at a similar timepoint to Fars2 knockout mice." (PMID 37274208, 2023). "Since the first case was reported in 2012, an increasing number of FARS2 variations have been subsequently identified, which present three main phenotypic manifestations: early onset epileptic encephalopathy, hereditary spastic paraplegia, and juvenile-onset epilepsy." (PMID 38166857, 2024).
Spastic paraplegia (5 papers, 2019 to 2024). Complete loss of the ability to move the lower limbs accompanied by spasticity of the lower limbs. "Here, we reported two affected siblings in an autosomal recessive spastic paraplegia family with a pseudo‐homozygous missense variant and Alu‐mediated exon 5 deletion in FARS2." (PMID 39342436, 2024). "Mutations in FARS2 are similarly linked to neurological disease including infantile-onset mitochondrial encephalopathy and spastic paraplegia." (PMID 37274208, 2023). "Approximately 44 subjects with disease-causing variants in FARS2 have been reported, including 27 cases of early-onset encephalopathy with or without epilepsy, 3 cases of juvenile-onset epilepsy, and 14 cases of spastic paraplegia." (PMID 36155627, 2022). "Previous reports have described two distinct phenotypes linked to FARS2 gene mutation: an early onset epileptic encephalopathy and spastic paraplegia." (PMID 32774346, 2020). "Review of the literature demonstrates that homozygous or compound heterozygous FARS2 pathogenic variants are responsible for three distinct clinical phenotypes, including early-onset epileptic encephalopathy, spastic paraplegia, and the latest report of juvenile-onset refractory epilepsy." (PMID 36155627, 2022). "Likewise, expression of a human FARS2 variant linked to epileptic encephalopathy exacerbated the seizure phenotype of PheRS-m knockout Drosophila, while expression of a pathological variant associated with spastic paraplegia impaired climbing activity." (PMID 37274208, 2023).
Alpers syndrome (3 papers, 2014 to 2021). A cerebral degeneration that results in progressive degeneration of grey matter in the cerebrum and has_symptom convulsions. "Variants in PARS2, CARS2, GABRB2, FARS2, and NARS2 were also reported in Alpers’ syndrome patients." (PMID 34690748, 2021). "In recent years, with the advancement of genetic testing technology, Alpers syndrome caused by NON-POLG genes has also been continuously reported, including mitochondrial aminoacyl transfer RNA synthetase related genes (PARS2, CARS2, FARS2 and NARS2) and γ-GABA receptor related genes Gene (GABRB2)." (PMID 34690748, 2021).
epilepsy (3 papers, 2014 to 2025). A brain disorder characterized by episodes of abnormally increased neuronal discharge resulting in transient episodes of sensory or motor neurological dysfunction, or psychic dysfunction. "Since then, a growing number of FARS2 deleterious variants have been identified in three different disorders: COXPD14 with early-onset encephalopathy with or without epilepsy, COXPD14 with juvenile-onset epilepsy, and spastic paraplegia type 77 (SPG77, MIM: 617046)." (PMID 36155627, 2022).
Brain atrophy (2 papers, 2022 to 2023). Partial or complete wasting (loss) of brain tissue that was once present. "In early-onset epileptic encephalopathy patients with FARS2 mutations, global brain atrophy, and cortical atrophy in particular, is a general MRI change in the later course of the disease." (PMID 35794642, 2022). "Fars2-cKO mice exhibit severe structural abnormalities within the brain during subsequent embryonic development, including enlargement of the ventricles and cortical degeneration, consistent with the occurrence of brain atrophy in multiple human patients with biallelic FARS2 mutations." (PMID 37274208, 2023).
cardiomyopathies (2 papers, 2024). "As a consequence, our findings provide new insights into the molecular diagnosis and prevention of heritable cardiomyopathy, as well as therapeutic options for FARS2-associated cardiomyopathy." (PMID 38362779, 2024). "Our results highlight the importance of the MQC system dysregulation in the pathological remodeling of cardiac hypertrophy caused by FARS2 deficiency and the potential therapeutic approaches in FARS2 or mtARS-associated cardiomyopathy." (PMID 38362779, 2024). "This should involve studies using alternative models to comprehensively validate the effectiveness of targeting the MQC system in the treatment of FARS2-associated cardiomyopathy and mitochondrial translation deficiency–related HCM." (PMID 38362779, 2024). "We identified FARS2 as a potential novel pathogenic gene in cardiomyopathy and investigated its effects on mitochondrial homeostasis and the cardiomyopathy phenotype." (PMID 38362779, 2024). "We report that FARS2 is a potential pathogenic gene related to cardiomyopathy." (PMID 38362779, 2024). "This study may provide new insights into the molecular diagnosis and prevention of heritable cardiomyopathy as well as therapeutic options for FARS2-associated cardiomyopathy." (PMID 38362779, 2024). "Recently, FARS2 was identified as a potential pathogenic gene to cause cardiomyopathy." (PMID 39342436, 2024). "Nonetheless, we cannot exclude that regulation of the upstream signals of the MQC system could represent a potent strategy for treating cardiomyopathy induced by FARS2 deficiency." (PMID 38362779, 2024). "To elucidate the role of FARS2 in the heart, we first analyzed the RNA sequencing data of multiple types of cardiomyopathies and HF in human and mouse models." (PMID 38362779, 2024). "FARS2 expression was substantially downregulated in HF and cardiomyopathies, including HCM, demonstrating that FARS2 deficiency may be the pathogenic mechanism of cardiomyopathies and HF." (PMID 38362779, 2024).
neuropathy (2 papers, 2015 to 2022). A disorder affecting the nervous system that manifests with pain, tingling, numbness, and/or muscle weakness. "To sum up, we have successfully established mouse and zebrafish models of Fars2 deficiency that mimic the neuropathy and metabolism changes seen in human patients." (PMID 35794642, 2022). "However, the underlying pathogenesis of neuropathy-associated Fars2 deficiency is still largely unknown." (PMID 35794642, 2022). "These evidence suggests that in addition to mitochondrial dysfunction, disruption of retrograde axon transport induced by Dctn3 reduction might be another possible pathogenesis of Fars2-related neuropathy." (PMID 35794642, 2022).
paraplegia (2 papers, 2022 to 2024). Complete paralysis of the lower half of the body including both legs, often caused by damage to the spinal cord. "The strong degeneration of motor neurons in zebrafish, and excessive neuronal death within the motor cortex in Fars2-deficient mouse models, clarified the spastic paraplegia phenotype observed in human patients with FARS2 mutations." (PMID 35794642, 2022).
asthma (1 paper, 2013). "Human associations for this region most strongly support the phenylalanyl-tRNA synthetase 2, mitochondrial (FARS2) gene as involved in asthma, with an EVE Latino American p-value of 6.4e-04 at rs9502304." (PMID 23457522, 2013).
Atrophy (1 paper, 2022). Any weakening or degeneration, especially through lack of use. "The present data show that Fars2-deficient mouse embryos have a thinner cortex and an enlarged ventricle; these correspond to the neural atrophy observed in human brain." (PMID 35794642, 2022).
autosomal recessive spastic paraplegia (1 paper, 2023). "FARS2 variants cause autosomal recessive spastic paraplegia." (PMID 36781956, 2023).
breast carcinoma (1 paper, 2024). "Elevated expressions of FARS2 and TRUB2 have been noted in breast cancer tissues, and C2orf15 expression significantly correlates with breast cancer prognosis, although their link to ER status needs further investigation." (PMID 39720180, 2024).
cardiac hypertrophy (1 paper, 2024). "We confirmed that FARS2 deficiency directly drives cardiac hypertrophy, HF, and sudden death on the basis of mouse and zebrafish models." (PMID 38362779, 2024). "FARS2 deficiency results in cardiac hypertrophy by impairing mitochondrial homeostasis and disrupting the MQC system." (PMID 38362779, 2024). "An important finding of this study is that dysregulation of the MQC system plays a crucial role in the pathological remodeling of cardiac hypertrophy and HF triggered by FARS2 deficiency." (PMID 38362779, 2024). "To investigate the mechanisms underlying the cardiac hypertrophy induced by FARS2 ablation, we next examined the myocardial and mitochondrial functions in the early and late stages (3 and 10 weeks after icKO, respectively) in icKO and WT control littermates." (PMID 38362779, 2024). "FARS2 deficiency increased the cardiomyocyte cross-sectional area and cardiac hypertrophy, whereas AAV-Drp1i and AAV-Mfn1 mitigated these changes." (PMID 38362779, 2024). "Heart-specific Fars2-deficient mice presented cardiac hypertrophy, left ventricular dilation, progressive heart failure accompanied by myocardial and mitochondrial dysfunction, and a short life span." (PMID 38362779, 2024). "In addition, we confirmed that inhibition of mitochondrial-associated autophagy or mitochondrial dynamics could provide functional and morphological benefits in FARS2-related cardiac hypertrophy by restoring mitochondrial dyshomeostasis." (PMID 38362779, 2024).
dysplasia (1 paper, 2022). A usually neoplastic transformation of the cell, associated with altered architectural tissue patterns. "Furthermore, transcriptome sequencing analysis revealed that the Fars2-defect induced neuronal dysplasia may closely related to the activation of axon sheathing process and NF- κB signaling pathway during neuron development." (PMID 35794642, 2022).
early-onset epilepsy (1 paper, 2014). "We have identified a patient with early-onset epilepsy and isolated complex IV deficiency due to mutations in the FARS2 gene, prompted by diagnostic array CGH studies that identified a heterozygous interstitial 6p25.1 deletion." (PMID 24161539, 2014).
hypertrophic cardiomyopathy (1 paper, 2024). A condition in which the myocardium is hypertrophied without an obvious cause. "The differentially expressed genes were also enriched in cardiac muscle contraction and hypertrophic cardiomyopathy, in good agreement with the cardiac morphology of FARS2-deficient models." (PMID 38362779, 2024).
migraine (1 paper, 2022). "Therefore, the causal effect of lower levels of FARS2 on migraine suggests higher levels of free phenylalanine in migraine patients." (PMID 35546551, 2022). "Additionally, our LCV analyses found a significant genetic causality on migraine for lower levels of three blood proteins, including FARS2, GSTA4 and CHIC2." (PMID 35546551, 2022). "We show that higher levels of DKK1 and PDGFB, and lower levels of FARS2, GSTA4 and CHIC2 proteins have a significant causal effect on migraine." (PMID 35546551, 2022). "Lastly, our scan for inferring causality identified five blood proteins (DKK1, PDGFB, GSTA4, FARS2 and CHIC2) with a significant genetic causality on migraine." (PMID 35546551, 2022). "In addition, we identified that higher levels of DKK1 and PDGFB, and lower levels of FARS2, GSTA4 and CHIC2 causally increase the risk of migraine." (PMID 35546551, 2022).
Obesity (1 paper, 2016). Accumulation of substantial excess body fat. "FARS2 is a suggestive locus (p<10−7) for severe early-onset obesity." (PMID 27537407, 2016).
status epilepticus (1 paper, 2024). Status epilepticus is defined as a continuous seizure lasting more than 30 min, or two or more seizures without full recovery of consciousness between any of them. "CCD can appear in patients with status epilepticus, which is mainly related to chronic focal epilepsy and may be related to additional cross-nerve excitatory toxicity damage; it has not been reported in patients with FARS2 gene mutations." (PMID 38166857, 2024).
cancer (4 papers, 2018 to 2023). A tumor composed of atypical neoplastic, often pleomorphic cells that invade other tissues. "More interestingly, FARS2 is down-regulated in KICH, while the two paralog ARSs, FARSA and FARSB, are up-regulated in six and four cancer types, respectively." (PMID 30588513, 2018).
mitochondrial disease (4 papers, 2014 to 2022). "Using steady‐state kinetic measurements of phenylalanine activation and tRNAPhe aminoacylation, we gained insight into the structural and kinetic effects of mitochondrial disease‐related mutations in FARS2 gene." (PMID 28419689, 2017).
neurodegenerative disease (3 papers, 2021 to 2024). A disorder of the central nervous system characterized by gradual and progressive loss of neural tissue and neurologic function. "In addition, the interaction between the pathogenesis of neurodegenerative diseases and impairment of angiogenesis caused by FARS2 defects requires further exploration." (PMID 34540921, 2021).
infection (2 papers, 2022 to 2025). The state of being infected such as from the introduction of a foreign agent such as serum, vaccine, antigenic substance or organism. "To identify the molecular mechanisms and the dynamic changes underlying the neurodegenerative phenotypes caused by Fars2 deficiency, we performed RNA-seq analysis at 1,3,5,7, and 10 days after infection using mouse primary cultured neurons." (PMID 35794642, 2022). "The length of the longest primary neurite of neurons with Fars2 knocked-down, was relatively normal following four days of culture after infection; but with a slighter figure and fewer secondary branches than in the control group." (PMID 35794642, 2022). "GSEA of primary cultured neuron transcriptomes revealed that genes involved in axon ensheathment are upregulated in Fars2 knocked-down group at 7th day after infection, and genes involved in NF-κB signaling pathway are upregulated in Fars2 knocked-down neurons at 10th day after infection." (PMID 35794642, 2022).
neurological diseases (2 papers, 2021 to 2024). "Although mutations in the FARS2 gene have a strong association with neurological diseases, the relationship between neural microvascular networks and disease phenotypes in patients with these mutations has not been characterized." (PMID 34540921, 2021). "Several variants of FARS2 have been suggested to cause neurological disorders; however, FARS2-associated diseases involving other organs have not been reported." (PMID 38362779, 2024).
cardiovascular disease (1 paper, 2021). "Here we examined the role of mitochondrial phenylalanyl-tRNA synthetase (FARS2) in developmental angiogenesis and its potential contribution to the pathogenesis of cardiovascular disease." (PMID 34540921, 2021).
genetic diseases (1 paper, 2021). "Our study may provide new insights into the progression of neurovascular diseases and the diagnosis and treatment of FARS2 mutation-related genetic diseases." (PMID 34540921, 2021).
neurodevelopmental disorder (1 paper, 2019). A behavioral and cognitive disorder with onset during the developmental period that involves impaired or aberrant development of intellectual, motor, or social functions. "Four of the inherited heterozygous deletions affected known recessive disease genes, of which two, FARS2 (MIM 611592) and SPATA5 (MIM 613940), have been associated with neurodevelopmental disorders." (PMID 30552426, 2019).
FARS2 also shares sentences with these, for which no sentence is quoted: Epileptic encephalopathy (3 papers); Leukoencephalopathy (3); early onset epileptic encephalopathy (2); Encephalopathy (2); infantile spasms (2); interstitial lung disease (2); Tumor (2); amyotrophic lateral sclerosis (1); Arthritis (1); attention deficit-hyperactivity disorder (1); autism spectrum disorder (1); autosomal recessive spastic ataxia (1); Autosomal recessive spastic ataxia with leukoencephalopathy (1); bipolar disorder (1); Cerebral atrophy (1); cervical cancer (1); cortical atrophy (1); eating disorder (1); focal epilepsy (1); gastric cancer (1); glycogen storage diseases (1); heart diseases (1); heart failure (1); hypothyroidism (1); Insulin resistance (1); lactic acidosis (1); Leigh syndrome (1); leukodystrophies (1); liver disease (1); liver dysfunction (1).
A further 15 diseases each share a sentence with FARS2 in 1 paper.